DAZ1 (deleted in azoospermia 1)
Description:
RNA-binding protein that plays an essential role in spermatogenesis. May act by binding to the 3'-UTR of mRNAs and regulating their translation. Promotes germ-cell progression to meiosis and formation of haploid germ cells.
Synonyms: DAZ; SPGY
Tractability: PROTAC: ubiquitination databases record sites on it.
Gene: Protein-coding gene on chromosome Y (23,129,355 to 23,199,010, reverse strand). Ensembl gene ENSG00000188120.
Subcellular location: Cytoplasm; Nucleus
Gene Ontology:
Molecular function: protein binding; translation activator activity; mRNA 3'-UTR binding; nucleic acid binding; RNA binding
Biological process: positive regulation of translational initiation; 3'-UTR-mediated mRNA stabilization
Cellular component: cytoplasm; nucleus; protein-containing complex
Homologues: Orthologues: dog DAZL (26% identical), guinea pig DAZL (22% identical), tropical clawed frog dazl (16% identical), zebrafish dazl (12% identical), Caenorhabditis elegans daz-1 (10% identical), Drosophila melanogaster bol (8% identical). Paralogues in human: DAZ4 (77% identical), DAZ2 (55% identical), DAZ3 (54% identical), DAZL (24% identical), BOLL (10% identical).
Diseases named in the same sentence as DAZ1 in open-access papers:
DAZ1 is named in the same sentence as 9 diseases in open-access papers, as found by Europe PMC text mining. Sharing a sentence is not in itself a finding about the gene and the disease. The quoted sentences say what the papers report.
Azoospermia (18 papers, 2008 to 2025). Absence of any measurable level of sperm,whereby spermatozoa cannot be observed even after centrifugation of the semen pellet. "The loss of the deleted in azoospermia (DAZ) genes DAZ1, DAZ3, and DAZ4 leads to spermatogenic arrest, contributing to male infertility." (PMID 40391511, 2025).
Infertility (8 papers, 2008 to 2022). "We detected 38 out of 50 infertile men (3.9%) and 6 out of 9 fertile men (1.02%) with the absence of the sY1291, DAZ cluster I (DAZ1 + 2), and CDY1a, which show the g1/g2 and r1/r3 (Fig. 1FII) NAHR patterns." (PMID 31000748, 2019).
male infertility (8 papers, 2007 to 2025). The inability of the male to effect fertilization of an ovum after a specified period of unprotected intercourse. "DAZ1/DAZ2 deficiency is associated with male reproductive dysfunction and may be a risk factor for male infertility." (PMID 39850494, 2024). "Moreover, we investigate the Y-chromosome genes, DAZ1/DAZ2/DAZ3/DAZ4, of which structural variants have been linked to male infertility, and X-chromosome genes OPN1LW and OPN1MW linked to eye disorders." (PMID 37365340, 2023).
gastric cancer (1 paper, 2021). A primary or metastatic malignant neoplasm involving the stomach. "The results showed that DAZ1, WIPF3, RBPMS2, and NOVA1 were low expressed in gastric cancer (P<0.05), and KIAA0101 and COL5A2 were highly expressed (P<0.05)." (PMID 34234866, 2021).
Sertoli Cell-Only Syndrome (1 paper, 2025). A type of male infertility in which no germ cells are visible in any of the biopsied SEMINIFEROUS TUBULES (type I) or in which germ cells are present in a minority of tubules (type II). "Secondly, three IR-rich genes (USP9Y, DDX3Y, DAZ1), or their protein products, play a significant role in Sertoli cell-only syndrome (DOID:0050457)." (PMID 41155472, 2025).
tumor (1 paper, 2022). "Furthermore, data mining of RNA-Seq data of 27 male tumor/non-tumor paired samples from The Cancer Genome Atlas (TCGA) showed that DAZ1 and BPY2 are frequently down-regulated in HCC patients." (PMID 34983649, 2022).
DAZ1 also shares sentences with these, for which no sentence is quoted: oligospermia (2 papers); cancer (1); Turner syndrome (1).